STAT3 (signal transducer and activator of transcription 3)
Diseases named in the same sentence as STAT3 in open-access papers (continued):
Sharing a sentence is not in itself a finding about the gene and the disease.
cancer (continued). "Besides Stat3 downstream signaling, IL-6 also activates Phosphoinositide 3-kinase (PI3K)/Akt pathway, which was shown to promote cancer progression." (PMID 30224299, 2018). "Further investigation of the relationship between JAB1 and multiple oncogenic transcription factors containing STAT3 may enhance our knowledge of JAB1-mediated regulatory mechanisms and lead to the development of effective anti-cancer drugs." (PMID 29914167, 2018). "The STAT3 transcription factor, a known driver of cancer progression, is often over active in HPV-associated cancers; however, its role in the life cycle of HPV has not been studied." (PMID 29630659, 2018). "In conclusion, the results indicated that shikonin sensitized resistant cancer cells to TRAIL-induced cytotoxicity via the modulation of the JNK, STAT3 and AKT pathways, the downregulation of antiapoptotic proteins and the upregulation of proapoptotic proteins." (PMID 30594131, 2018). "In cancer cells such as DU145, MDA-MB-231, and U266, they showed that genipin could inhibit the constitutive signal-transducer-and-activator-of-transcription-3 (STAT3) activation by suppressing upstream Janus kinase 1 (JAK1) and c-Src." (PMID 29587429, 2018). "STAT3 and AKT are key molecules constituting significant anti-apoptotic pathways in many cancers." (PMID 29867489, 2018). "Increasing evidence demonstrates that the JAK/STAT3, PI3K/AKT and MEK/ERK pathways are frequently activated by adipokines, such as IL-6 and leptin and that these pathways are often altered in several types of cancer." (PMID 30563531, 2018). "Nonetheless, CSCs are responsible for cancer cell metastasis, drug resistance, and tumor relapse, perturbing VEGFR2/STAT3/Myc/Sox2 axis might be useful in overcoming the chemo-resistance in triple-negative breast cancer." (PMID 29455658, 2018). "Pervanadate, a pharmacologic phosphatase inhibitor, was used previously to validate the inhibitory effect of SHP-1 in STAT3-activated cancer In this study, pervanadate was used to investigate the role of SHP-1 in the dephosphorylation of JAK2/STAT3 and the anti-EMT effect of ATO." (PMID 29409467, 2018). "The lack of effect of STAT3 inhibition on GBM10 migration suggests STAT3 targeting as a strategy to impair cancer migration effective only for certain patient populations within GBM." (PMID 29566069, 2018). "Thus, STAT3 is capable of exacerbating β-catenin and inducing PDGFA to promote Wnt signaling for maintaining the formation and survival of cancer stem-like tumorspheres in selective EGFR-positive CRCs." (PMID 30068339, 2018). "STAT3 activation, which propagates from cancer cells into non-malignant immune cells infiltrating tumors, is known to play an important role in promoting these tolerogenic effects." (PMID 29921770, 2018). "Activation of STAT3 by mTORC1 promotes survival and cancer stem-like cell properties a phenotype not observed in macrophages expressing Myo1F." (PMID 30687322, 2018). "The outcome of STAT3 activation, however, is almost the exact opposite of STAT1 (despite almost 70% sequence homology, and similar crystal structure as tyrosine phosphorylated dimers) and contributes to carcinogenic processes and cancer progression." (PMID 30109213, 2018). "Our novel findings also showed that BAY 11‐7082 suppressed the acidic bile‐induced miR‐192 levels in treated human hypopharyngeal cells with strong positive correlations between BAY 11‐7082‐induced miR‐192 levels and inflammatory and key cancer molecules, such as RELA(p65), STAT3 and TNF‐α." (PMID 29516639, 2018). "Considering the previously established role of STAT3 in cancer metastasis, we hypothesized that PLOD3 promotes metastasis in a STAT3-dependent manner in the model system used herein." (PMID 30442941, 2018). "For instance, administration of a series of dual inhibitors of HIF-1α and STAT3 (in the absence of anticancer agent) resulted in significant anti-proliferative activity across a panel of various cancer cell lines." (PMID 30347860, 2018).
cancer (continued). "In multivariate analysis there was a trend toward significance in STAT3 (p = 0.090) and nuclear STAT3 (p = 0.079) for cancer-specific survival but not for progression-free survival." (PMID 30091994, 2018). "STAT3 is a member of the Signal Transducer and Activator of Transcription (STAT) family of transcription factors, which is constitutively activated in various cancers, including GBM." (PMID 29774125, 2018). "Recombinant IL-6 and MF-CM activated STAT3 and upregulated TGF-β in cancer cells." (PMID 28819126, 2017). "This may be explained by direct repression of RBM47 via the EMT-inducers STAT3 and SNAIL, which are generally activated in mesenchymal-like, invasive cancer cells." (PMID 28680090, 2017). "Currently, no STAT3 inhibitors for cancer therapy have yet been approved, regardless of the mechanisms of STAT3 inhibition." (PMID 28594363, 2017). "Thus, STAT3, TWIST and AKT form a functional signaling axis that regulates pivotal oncogenic properties of cancer cells." (PMID 28061440, 2017). "LLL12 exhibits high specificity for inhibiting STAT3 phosphorylation and dimerization, and inducing apoptosis to constitutively activated STAT3 cancer cells without cytotoxicity to normal cells with dormant STAT3." (PMID 28322306, 2017). "IL-6/STAT3 pathway has been confirmed to induce EMT and metastasis in many types of cancers." (PMID 28903339, 2017). "The TRIM8/STAT3 positive feedback loop in GBM provides new insight into the regulation of STAT3 and offers new opportunities for the development of treatments that impair stemness in GSC and potentially in other cancers that show TRIM8 overexpression." (PMID 29182544, 2017). "Stat3, is one out of seven members of the signal transducer and activator of transcription (STAT) family of transcription factors, a family of proteins which has been found to be constitutively activated in numerous cancer types." (PMID 29190807, 2017). "Thus, we conclude that TNF-α/TNFR1 activates the NF-κB (and/or p38)/STAT3/HBXIP signaling, leading to the development of cancer." (PMID 28938560, 2017). "Overexpressing miR-196b-5p promotes, while silencing miR-196b-5p inhibits the cancer stem cell properties and chemotherapeutic resistance via targeting negative regulators SOCS1 and SOCS3 of STAT3 signaling pathway, leading to the activation of STAT3 signaling." (PMID 28591704, 2017). "OPN secreted by TM4SF4/GSK3β/β-catenin signaling activated the JAK2/STAT3 or FAK/STAT3 pathway, which also up-regulates OPN expression in an autocrine manner and consequently maintains the self-renewal and metastatic capacity of cancer cells." (PMID 29254164, 2017). "Thus, our results suggested that low expression of miR-375 activates JAK2/STAT3 and MAP3K8/ERK pathways in cancer cells, which in turn promotes cell proliferation." (PMID 28186962, 2017). "How STAT3 confers HICR also may be related to its ability to upregulate CD44, a marker of cancer stemness." (PMID 29036915, 2017). "Similarly, STAT3 has been shown to work with HIF1α in order to activate downstream targets in various cancers, and we have previously shown that APE1 interacts with both STAT3 and HIF1α under hypoxia." (PMID 28922540, 2017). "Since Wnt5-Frizzled2 could activate STAT3 phosphorylation in cancer cells and increase CSC properties, we further checked the activation of STAT3." (PMID 28367998, 2017). "Subsequently, p-STAT3 can induce the downstream target genes, such as CCL2, CCL5, ICAM-1, SNAI1, chitinase-3-like 1 (CHI3L1), FBJ murine osteosarcoma viral oncogene homolog (FOS), and Skp2, that promote various cellular processes for cancer progression." (PMID 28157698, 2017). "Of note, C10 did not affect STAT3S727 phosphorylation thus reflecting individual variations of STAT3 phosphorylation among different cancers (data not shown)." (PMID 29371911, 2017).
cancer (continued). "For example, the STAT3 transcription factor induces the expression of matrix metalloproteinase 2 (MMP-2), MMP-9, and epithelial–mesenchymal transition-related genes in promoting cancer cell invasion and metastasis." (PMID 28856117, 2017). "This binding leads to the recruitment of the signal transducing subunit gp130 and subsequently activates signal transducer and activator of transcription 3 (STAT3), which is the most common member of the STAT protein family and consistently constitutively activated in cancers." (PMID 28388577, 2017). "The results indicated that multiple genes and transcriptional factors related to cancer apoptosis and progression, such as Bak1, Bcl-2, KLF13 and STAT3, might be the target genes of miR-125b." (PMID 28176874, 2017). "Although STAT3 is an intriguing therapeutic target for cancer therapy, none of its inhibitors are clinically successful because of low potency or poor druggability." (PMID 28637459, 2017). "Given that Stat3 and CD133 are of importance in the regulation of proliferation and development of chemotherapeutic resistance, our results suggest meisoindigos as promising anti-cancer agents." (PMID 32961646, 2017). "In addition, excessive ROS affects various signaling pathways in cancer cells, including Akt, ERK, JNK, p38, NFκB, and STAT3." (PMID 28245605, 2017). "STAT3, one of the pathway strongly sustained by ROS, is constitutively activated in PEL cells and plays a fundamental role for the survival of these cells, as well as of several other cancer cell types." (PMID 29179721, 2017). "Together with the cancer cell they are a source for immunosuppressive factors like IL-6, IL-11, COX2 and also for VEGF, all of which are STAT3 induced as well as being inducers of immunosuppressive STAT3 signaling." (PMID 28402937, 2017). "Interestingly, short interfering RNA (siRNA)-mediated REP1 knockdown-induced growth inhibition of cancer cell lines via downregulation of EGFR and inactivation of STAT3, but had a negligible effect on normal cell lines." (PMID 28230863, 2017). "A systematic study of naphthoquinone derivatives with inhibitory activity against Stat3 signaling in cancer stem cells disclosed a novel class of furanonaphthoquinone molecules with inhibitory activity against cancer stem cell proliferation." (PMID 29056905, 2017). "The competitive pull-down assay with Bio-BENDA that was newly designed and synthesized to investigate the interaction between BENDA and cellular STAT3 indicated that BENDA tightly bound to STAT3 but not STAT1 in cancer cells." (PMID 28125678, 2017). "In contrary, the level of the phosphorylated STAT3 was not affected by PMM-172 in non-cancer MCF-10A cells." (PMID 28588262, 2017). "While the direct gene targets of STAT3 are subtype specific across TNBC, indicative of the heterogeneity of this disease, our findings suggest this factor plays a universal role of regulating invasion in this cancer." (PMID 28030809, 2017). "Signal transducer and activator of transcription 3 (STAT3) is a member of the STAT family, which is important for development, apoptosis, proliferation, cell cycle progression, angiogenesis, inflammation, and cancer metastasis." (PMID 28245605, 2017). "Notably, AT1R transactivates EGFR in several cancers, leading to extracellular-regulated kinase (ERK) activation, phosphorylation of signal transducer and activator of transcription 3 (STAT3) and activation of protein kinase C (PKC)." (PMID 28052030, 2017). "Many publications suggested that STAT3 and ERK/MAPK pathways are involved in the regulation of cell proliferation, apoptosis, and angiogenesis and participants in the processes of induction, progression, and metastasis of carcinoma." (PMID 29234375, 2017). "Furthermore, macrophage AEG-1 activated STAT3-MMP-9 pathway in FaDu cells, ultimately promoting cancer cell invasion." (PMID 27793010, 2016).
cancer (continued). "These investigations into gammaherpesviruses and STAT3 have simultaneously revealed a novel function for STAT3 in suppression of the DDR, a process fundamental to physiologic cell proliferation as well as development of cancer." (PMID 27458446, 2016). "Furthermore, STAT3 activation in EOC cells was also suppressed by combined treatment with ONA and each anti-cancer drug." (PMID 27404320, 2016). "To summarize, suppression of STAT3 and activation of SOCS3 would inhibit cancer cell growth." (PMID 26982332, 2016). "Grivennikov and Karin postulated STAT3-mediated nuclear NF-κB activation plays an important role in the pathogenesis of cancer and neurodegenerative disease, despite the fact NF-κB is not the only transcription factor that cooperates with STAT3." (PMID 27977755, 2016). "Consistent with the no-feeder cell culture system, the Stat3 signaling pathway was inhibited in cancer cells treated with preconditioned medium only when ES cells were present." (PMID 27460364, 2016). "Signal transducer and activator of transcription (STAT) proteins, particularly STAT3 and STAT5, are constitutively activated in a large number of human cancers, where their sustained activity contributes to dysregulated proliferation, apoptosis, angiogenesis, and immune surveillance." (PMID 27513743, 2016). "Inhibition of leptin STAT3 signaling, achieved by administration of leptin antagonists, by leptin receptor monoclonal antibodies, or by upregulating SOCS3 would facilitate apoptosis and impede cancer cell growth." (PMID 26982332, 2016). "In the present study, we found that ONA treatment significantly led to the sensitization of EOC cells to the anti-cancer agents PTX, CBDCA and CDDP, which suggested that ONA potentially reduced the stem cell properties of EOC cells by inhibiting STAT3 signalling." (PMID 27404320, 2016). "STAT3 is frequently hyperactivated by Y705 phosphorylation in HNSCC and other cancers." (PMID 27855189, 2016). "In cancer cells, Stat3 has been shown to act as either a positive or a negative regulator of mitochondrial activity depending on specific post‐translational modifications." (PMID 26903601, 2016). "Moreover, OV suppressed cell invasiveness and interfered with cell-matrix adhesion in Mia-PaCa2 cancer cells by reducing MMP-9 and FAK transcription through suppressing NF-κB and STAT3 pathway." (PMID 27242913, 2016). "Thus, identification of novel pharmacological agents which inhibit STAT3 and STAT5 activation have promise and potential in prevention and therapy of cancer." (PMID 26911335, 2016). "Our findings suggest that high levels of BIS expression might confer stem-cell-like properties on cancer cells through STAT3 stabilization, indicating that BIS is a potential target in cancer therapy." (PMID 27145367, 2016). "The detailed mechanisms of Lip-FLLL32 modulating those genes, dependent or independent of STAT3 inhibition, selectively in cancer or not, are still under investigation." (PMID 26887043, 2016). "High IL‐6 levels and activation of IL‐6:STAT3 signaling has been reported to induce a cancer stem cell phenotype to nonstem cells 28, while IL‐6 trans‐signaling (through IL‐6:IL‐6R) has itself been implicated in 4T1 metastasis." (PMID 26725371, 2016). "Inflammatory pathways can trigger epigenetic switches from nontransformed to metastatic cancer cells via signalling involving NF κB and STAT3 transcription factors, microRNAs (Lin28 and let-7), and IL-6 cytokines." (PMID 27608040, 2016). "For elucidation of the upstream signalling pathways that regulate STAT3 activation at S727, we first showed that enriched TICs did not increase the protein levels of important kinases, such as AKT, P38, JNK and ERK compared with bulk cancer cells." (PMID 27306323, 2016). "While IL-17 upregulation of STAT3 was shown to be mediated by IL-6 other cancer types, this phenomena did not hold true in this case." (PMID 27784305, 2016).
cancer (continued). "It is known that the activation of STAT3 in cancers leads to gene expression promoting cell proliferation and resistance to apoptosis, but 15d-PGJ2-induced SOCS3 overexpression may have prevented STAT3 phosphorylation." (PMID 27190500, 2016). "This network also includes accepted cancer markers, such as TNF, STAT3, NF-κB and IL6." (PMID 27685442, 2016). "Again, similar to non-viral cancers, STAT3 contributes to gammaherpesvirus (EBV and KSHV)-mediated cancers by driving cell proliferation, invasion and angiogenesis." (PMID 27458446, 2016). "To determine whether STAT3 expression was regulated by OLA1P2, we infected cancer cells with a lentivirus expression vector (lenti-OLA1P2) or a short hairpin RNA vector (shRNA-OLA1P2)." (PMID 26898989, 2016). "Our model implicates high Stat3 and/or IL-6 levels in senescence-competent PCa and therefore does not contradict the general observation of high IL-6 and/or Stat3 expression in many cancers." (PMID 26198641, 2015). "Importantly, a subtoxic concentration of E804 resensitized cancer treatment-resistant cells (MV4-11-R) by inhibiting STAT1, STAT3, and STAT5 signaling and by abolishing survivin expression." (PMID 26457112, 2015). "However, cancer cells, including TNBC cells, frequently have inappropriate constitutive activation of STAT3, and can be dependent on STAT3 activity for survival." (PMID 26000098, 2015). "On the basis of the increased expression of p-STAT3 in human HNSCC, which is consistent with previously study, we hypothesized that STAT3 may play an important role in maintaining HNSCC cancer stem cell properties." (PMID 26556875, 2015). "Despite the presence of diverse regulators and pivotal biological functions in cancer, no effective therapeutic inventions are available for inhibiting STAT3 and acquiring potent antitumor effects in the clinic." (PMID 26631279, 2015). "STAT3 is reportedly not essential to the survival of normal cells, but is critical to many types of cancer cells, making it a potentially valuable therapeutic target." (PMID 26283544, 2015). "Since persistent STAT activation often occurs in cancer, we were interested whether the oncogenic activation of PDGFRα also leads to the activation of STAT1, STAT3 and STAT5 transcription factors." (PMID 25880691, 2015). "Numerous human cancer cell lines, including HT-29, do not constitutively express p-STAT3 in vitro, however, previous studies have demonstrated that IL-6 can stimulate STAT3 activation in HT-29 cells." (PMID 25789077, 2015). "Whereas LIF does not affect cell proliferation or invasion of cancer cells, it protects malignant cholangiocytes from chemotherapy-induced apoptosis via a STAT3- and MAPK-independent, PI3K/AKT-dependent Mcl-1 activation." (PMID 26296968, 2015). "This may not be entirely surprising since EML-ALK activates various downstream signaling molecules including ERK, STAT3, and AKT, which are the key elements in inducing and maintaining stem-like properties for both normal stem cells and cancer stem cells." (PMID 26517679, 2015). "In this context, we showed that treatment of MM cells with the STAT3 inhibitor STA-21 or with the JAK2-specific inhibitor AG490 can increase MICA expression, thus confirming the repressive action of STAT3 on this gene also in this type of cancer cells." (PMID 26161387, 2015). "Importantly, HDN-1 degrades multiple client proteins, such as EGFR, Stat3, Akt, Erk, Raf, Cyclin D1, and HIF, all of which have been reported to be oncoproteins to promote cancer development." (PMID 25742791, 2015). "We have recently shown that PL potently inhibits STAT3 activation in cancer cells and that STAT3 non-transcriptionally regulates collagen-induced platelet activation/aggregation by facilitating an interaction between the kinase Syk and the substrate PLCγ2." (PMID 26645674, 2015).